ANO5 (anoctamin 5)
Diseases named in the same sentence as ANO5 in open-access papers (continued):
Sharing a sentence is not in itself a finding about the gene and the disease.
muscular disease (4 papers, 2013 to 2024). Myopathy is a peripheral nervous system disease consisting of any abnormal condition or disease of the muscular tissues; commonly designates a disorder involving skeletal muscle. "Loss of function in ANO5 is a well-known mechanism of ANO5 muscular disease." (PMID 39457424, 2024). "ANO5 muscle disorders are rare, but their prevalence is relatively high in northern European populations because of the founder mutation c.191dupA." (PMID 36292621, 2022). "More diffusely severe myopathy in male patients assessed by MRC testing was reminiscent of some other muscular diseases of autosomal inheritance, such as FSHD, hypokalemic periodic paralysis (HypoPP) or ANO5 mutation-related myopathy." (PMID 26849574, 2016). "In addition, this patient bears no other major mutation in other 98 “muscular-disease” genes, but a single heterozygous ANO5 variation (Glu95Lys), without a clear significance." (PMID 23667635, 2013).
dilated cardiomyopathy (3 papers, 2022 to 2024). Cardiomyopathy which is characterized by dilation and contractile dysfunction of the left and right ventricles. "Homozygous mutations in ANO5, a gene encoding anoctamin 5, a putative calcium-activated chloride channel, have recently been reported in patients with adult-onset myopathies or an isolated high-CK level, and may appear to cause complications in the form of dilated cardiomyopathy." (PMID 37510237, 2023).
osteosarcoma (3 papers, 2016 to 2023). A usually aggressive malignant bone-forming mesenchymal neoplasm, predominantly affecting adolescents and young adults. "Furthermore, by performing loss and gain of function experiments, we found that ANO5 promoted proliferation and metastasis of osteosarcoma cells in vitro." (PMID 34238763, 2021). "In this study, bioinformatics analysis, western blot, and immunohistochemical staining revealed that ANO5 was upregulated in osteosarcoma cell lines and osteosarcoma tissues, and ANO5 expression was positively associated with tumor size, tumor grade, and metastasis." (PMID 34238763, 2021). "In the current study, bioinformatic analysis, western blots, and immunohistochemical staining demonstrated that ANO5 expression was higher in osteosarcoma tissues and cell lines than in adjacent tissues and hFOB1.19 cells." (PMID 34238763, 2021). "Functional experiments demonstrated that inhibition of ANO5 decreased, while ANO5 overexpression increased, osteosarcoma cell proliferation and mobility in vitro." (PMID 34238763, 2021). "The results showed that inhibition of ANO5 markedly reduced osteosarcoma cell proliferation rates in vivo." (PMID 34238763, 2021). "Taken together, these findings demonstrate that suppression of ANO5 decreased osteosarcoma cell proliferation and increased NELL1 and NELL2 expression in vivo." (PMID 34238763, 2021). "ANO5 expression was elevated in osteosarcoma and promoted the development of osteosarcoma cells by increasing degradation of the tumor suppressors NELL1 and NELL2." (PMID 34238763, 2021). "In this study, we found that ANO family member ANO5 was highly expressed in osteosarcoma tissues and cell lines and that it promoted the proliferation and metastasis of osteosarcoma cells by increasing the degradation of NELL1 and NELL2." (PMID 34238763, 2021). "Relationships between ANO5 expression and age, gender, tumor size, tumor grade, and metastasis in osteosarcoma patients were evaluated using a Chi-square test." (PMID 34238763, 2021). "Taken together, our current results demonstrate that ANO5 acted as a novel oncogene in osteosarcoma." (PMID 34238763, 2021). "We found that ANO5 promoted the proliferation and metastasis of osteosarcoma by increasing the degradation of NELL1 and NELL2." (PMID 34238763, 2021). "Using qRT-PCR and western blot, we found that ANO5 mRNA and protein levels were both elevated in osteosarcoma cells (U2OS, MG63, HOS, and Saos2) compared to the normal osteoblast cell line hFOB 1.19." (PMID 34238763, 2021). "NELL1 and NELL2, which act as suppressors in various types of cancer including osteosarcoma, were identified as proteins that interact with ANO5." (PMID 34238763, 2021). "Taken together, these in vitro experiments indicated that ANO5 acts as oncogene by promoting osteosarcoma cell proliferation and metastasis." (PMID 34238763, 2021). "Moreover, a subcutaneous tumor transplantation model revealed that ANO5 knockdown reduced osteosarcoma cell proliferation and increased NELL1 and NELL2 expression in vivo." (PMID 34238763, 2021). "Finally, rescue experiments showed that knockdown of NELL1 or NELL2 reversed the inhibitory effects of ANO5 knockdown on osteosarcoma cell proliferation and migration." (PMID 34238763, 2021). "Here, we explored the biological functions and molecular mechanisms of ANO5 in osteosarcoma." (PMID 34238763, 2021). "To determine whether NELL1 and NELL2 were involved in ANO5-induced osteosarcoma, we inhibited NELL1 or NELL2 expression in ANO5 knockdown cells." (PMID 34238763, 2021). "Although ANO5 expression is upregulated in various cancers, its role in osteosarcoma remains largely unknown." (PMID 34238763, 2021). "Furthermore, immunohistochemical staining of ANO5 in 40 paired osteosarcoma and adjacent normal tissues indicated that ANO5 was also elevated in osteosarcoma tissues." (PMID 34238763, 2021). "The results showed that ANO5 gene expression was markedly upregulated in osteosarcoma cell lines." (PMID 34238763, 2021).
osteosarcoma (continued). "Together, these results indicate that ANO5 may act as an oncogene in osteosarcoma." (PMID 34238763, 2021). "ANO5 might therefore be a potential target for osteosarcoma therapy." (PMID 34238763, 2021). "Furthermore, confocal microscopy demonstrated that ANO5 was colocalized with NELL1 and NELL2 in osteosarcoma cells." (PMID 34238763, 2021). "The STRING interaction network for ANO5 indicated that it interacted with NELL1 and NELL2, suggesting that these proteins may play a role in ANO5-induced proliferation and metastasis in osteosarcoma." (PMID 34238763, 2021).
Cementoma (2 papers, 2016 to 2022). An odontogenic tumor of the cementum of tooth. "A heterozygous mutation in the anoctamin 5 gene c.1067G > A (p.Cys356Tyr) was identified in both affected individuals in the Russian family with giant cementoma and bone fractures." (PMID 27216912, 2016).
colorectal cancer (2 papers, 2018 to 2021). A primary or metastatic malignant neoplasm that affects the colon or rectum. "Together, the potential combined effect of modulation of macrophages via efferocytosis and T-cells via PD-L1 expression, prime a favorable tumor-microenvironment raising the importance of dysregulation of CBL, CBLB, XKR4 and ANO5 in colorectal carcinoma." (PMID 30429477, 2018).
hypertrophic cardiomyopathy (2 papers, 2022 to 2023). A condition in which the myocardium is hypertrophied without an obvious cause. "Mutations in the ANO5 gene cannot only lead to myopathy but also to cardiac pathology with a phenotype of hypertrophic cardiomyopathy." (PMID 37510237, 2023). "Here, we report a case of a new phenotype in a carrier of ANO5 mutation NM_213599:c.2272C>T: the combination of myopathy with hypertrophic cardiomyopathy, complicated by post-COVID-19 myopericarditis." (PMID 37510237, 2023).
pancreatic cancer (2 papers, 2021 to 2023). "ANO5 expression is scarce in healthy pancreatic tissue, but it is elevated in pancreatic cancer, where it contributes to the disease’s proliferation and migration." (PMID 36836529, 2023).
prostate carcinoma (2 papers, 2020 to 2021). A carcinoma that arises from epithelial cells of the prostate gland. "We conducted a comprehensive analysis of anoctamin gene SNPs with prostate cancer recurrence and found that ANO5 rs4622263 was associated with unfavorable prognosis." (PMID 32027096, 2020). "Our genetic association study identified that ANO5 rs4622263 was associated with recurrence‐free survival in patients with prostate cancer following radical prostatectomy." (PMID 32027096, 2020). "Lower levels of ANO5 expression were associated with more aggressive forms of prostate cancer, higher Gleason score, pathologic stage, and shorter time to BCR/disease‐free survival in both cohorts." (PMID 32027096, 2020). "Taken together, ANO5 rs4622263 was associated with BCR, and ANO5 gene expression was correlated with patient prognosis, suggesting a pivotal role for ANO5 in prostate cancer progression." (PMID 32027096, 2020). "ANO5 may impede the progression of prostate cancer, and rs4622263 could be a promising prognostic biomarker for personalized therapies." (PMID 32027096, 2020). "Therefore, additional larger studies with multiethnic groups are needed to confirm our results, and further functional studies are also warranted to investigate the exact functions of rs4622263 or ANO5 on prostate cancer progression." (PMID 32027096, 2020). "Lower expression of ANO5 is correlated with worse BCR/disease‐free survival of prostate cancer." (PMID 32027096, 2020). "Moreover, lower expression of ANO5 was correlated with more advanced tumors and poorer outcomes in two independent prostate cancer cohorts." (PMID 32027096, 2020). "According to these results, we hypothesized that lower ANO5 and higher ANO10 expression would correlate with worse outcomes in prostate cancer." (PMID 32027096, 2020). "Also, we have not determined the precise mechanisms for the effect of ANO5 rs4622263 on prostate cancer progression, but functional annotation in HaploReg database provides clues to potential mechanisms, as described." (PMID 32027096, 2020).
atherosclerosis (1 paper, 2026). A disease characterized by the build-up of fatty material and calcium deposition in the arterial wall resulting in partial or complete occlusion of the arterial lumen. "Utilizing bulk RNA sequencing, six core efferocytosis-related genes (STAB1, ANO5, GULP1, LGR6, SCARF1, and CAMK2G) were identified, which exhibit significant diagnostic potential in atherosclerosis." (PMID 42272635, 2026).
Becker muscular dystrophy (1 paper, 2020). Becker muscular dystrophy (BMD) is a neuromuscular disease characterized by progressive muscle wasting and weakness due to degeneration of skeletal, smooth and cardiac muscle. "Chan also reported an increased risk of RM in patients with some hereditary neuromuscular diseases, such as Duchenne muscular dystrophy (DMD)/Becker muscular dystrophy (BMD), fukutin-related protein, dysferlin, γ-sarcoglycans, and anoctamin 5 deficiency-associated muscular atrophy." (PMID 33014933, 2020).
fibrous dysplasia (1 paper, 2023). A genetic, non-inheritable disorder caused by osteoblastic differentiation defects that result in the replacement of bone marrow and trabecular bone by fibrous stroma and immature bone. "No patients in the control group, including five patients with FCOD, five patients with polyostotic fibrous dysplasia, and eight patients with juvenile ossifying fibromas, carried mutated ANO5, suggesting that this type of mutation is uncommon in multifocal/multiquadrant fibro‐osseous lesions." (PMID 37649308, 2023).
gastric cancer (1 paper, 2023). A primary or metastatic malignant neoplasm involving the stomach. "In gastric cancer, ANO5 has been linked to a negative prognostic role; when it is knocked down, it causes apoptosis, reduces cell proliferation, and arrests the cell cycle at the G1/S transition." (PMID 36836529, 2023).
left ventricular hypertrophy (1 paper, 2015). Enlargement of the LEFT VENTRICLE of the heart. "We therefore compared the heart function of the Ano5 KO mice and their WT littermates under resting conditions or with isoproterenol (ISO)-induced left ventricular hypertrophy at 18 months of age." (PMID 26693275, 2015).
metabolic myopathy (1 paper, 2024). A group of rare inherited disorders characterized by a deficiency of enzymes that are involved in metabolic pathways that affect muscles. "The variant is absent in gnomAD and has been reported in trans with another ANO5 variant in an individual affected with pseudo-metabolic myopathy (ClinVar Accession: SCV000645874.5)." (PMID 39457424, 2024).
odontogenic tumor (1 paper, 2022). "ANO5 mutations must be related to abnormal odontogenic tumor development and/or to an epithelial–mesenchymal transition proposed to occur during normal root formation." (PMID 35982081, 2022).
Osteopenia (1 paper, 2022). Osteopenia is a term to define bone density that is not normal but also not as low as osteoporosis. "In this study, by measuring genotypes and phenotypes in a GDD family with low bone mass osteopenia, we report a de novo pathogenic ANO5 frameshift insertion mutation (c.1080_1081insGATTATTGGAGACTAAATAGTACGTGTTTG, p.L370_A371insDYWRLNSTCL)." (PMID 35982081, 2022). "We found a causative de novo ANO5 frameshift insertion mutation (p.L370_A371insDYWRLNSTCL) in a GDD family with osteopenia, accompanied by a decrease in TMEM16E expression and impaired RANKL-induced intracellular calcium ([Ca2+]i) oscillations in osteoclasts." (PMID 35982081, 2022).
osteoporosis (1 paper, 2022). A condition of reduced bone mass, with decreased cortical thickness and a decrease in the number and size of the trabeculae of cancellous bone (but normal chemical composition), resulting in increased fracture incidence. "By using 8-week-old Ano5 KO mice for animal models, we simulated the low-bone-mass GDD phenotype with osteoporosis at the age of onset." (PMID 35982081, 2022).
polyostotic fibrous dysplasia (1 paper, 2023). Fibrous dysplasia affecting more than one bone. "In addition, this mutation in ANO5 was confirmed to be absent in the control group, including five patients with FCOD, five patients with polyostotic fibrous dysplasia, and eight patients with juvenile ossifying fibromas." (PMID 37649308, 2023).
Sepsis (1 paper, 2023). Sepsis is defined as life-threatening organ dysfunction caused by a dysregulated host response to infection. "In addition, we identified in experimental sepsis another sepsis-suppressed gene linked to muscle dystrophy, anoctamin 5 (Ano5), and discovered its potentially beneficial regulation by the NTCI, Importantly, the treatment with the NTCI lowered the expression of Saa1 in the lungs by 2.7-fold." (PMID 37638006, 2023). "It is likely that the suppression of anoctamin 5 gene in sepsis may contribute to the Intensive Care Unit-Acquired Weakness (ICUAW) linked to the elevated Amyloid A-1-3 in sepsis." (PMID 37638006, 2023).
vacuolar myopathy (1 paper, 2015). "Other vacuolar myopathy related genes previously ruled out in these sporadic patients by Sanger sequencing were: GNE and ANO5 for patient 1s, GNE for 2s, GNE, ANO5 and MYH7 for 3s and GNE for 4s." (PMID 26205529, 2015).
Ventricular arrhythmia (1 paper, 2015). "Recent studies on the cardiac conduit system in ANO5 mutant patients also suggested an increased risk of ventricular arrhythmia." (PMID 26693275, 2015).
weakness (1 paper, 2024). "In Austria, the most frequent cause of limb-girdle muscular weakness and hereditary myopathy were pathogenic variants in CAPN3, FKRP, ANO5, DYSF, SGCA." (PMID 38758368, 2024).
myopathies (14 papers, 2012 to 2026). "In 2013, Wahbi and colleagues performed a comprehensive analysis of cardiac involvement in 19 patients from 16 families with isolated elevated CK or myopathy and a proven mutation in ANO5." (PMID 33567613, 2021). "We showed that ANO5 mutations (possibly in concerto with other variants in numerous genes linked with myopathies) are associated with the observed phenotypes." (PMID 31395899, 2019). "The manifestation of a limb-girdle type of myopathy seems to be much more frequent in ANO5 mutations (LGMD type 2L)." (PMID 23050857, 2012). "Late onset myopathy and asymptomatic isolated elevated CK have been reported in patients with homozygous mutation in ANO5 encoding the anoctamin protein family which mainly acts as a calcium-activated chloride channel and is expressed in both skeletal and cardiac muscles." (PMID 33567613, 2021). "Patients with ANO5 variants exhibited significantly later onset and shorter disease duration compared to CAPN3 and DYSF patients, emphasizing the relatively indolent course and late presentation of ANO5-related myopathy." (PMID 40870035, 2025). "The precise role played by ANO5 in membrane repair and the mechanism dysregulated in ANO5-myopathies remain to be elucidated." (PMID 34067866, 2021). "These two ANO5-KO mice did not present with an overt myopathy." (PMID 29789544, 2018).
tumor (6 papers, 2018 to 2023). "DNA was extracted from the tumor samples of all 21 patients after surgery, and mutations in exons 11 and 15 of ANO5 were detected." (PMID 37649308, 2023). "Finally, we found that high ANO5 expression was positively associated with tumor size, tumor grade, and metastasis." (PMID 34238763, 2021). "High ANO5 expression was positively associated with tumor size, tumor grade, and metastasis." (PMID 34238763, 2021). "Overall survival analysis of the ion channels using GEPIA in tumor state ion channels ANO5 (p-value: 0.16), LRRC8C (p-value: 0.48) and GLRB (p-value: 0.84) indicated high expression of genes correlated with poor survival." (PMID 35326596, 2022). "However, the expression of CACNA1F is very low in both tumor and normal tissues, and the prognostic value of ANO5 in PCa has previously been investigated." (PMID 36246559, 2022). "Furthermore, both NELL1 and NELL2 were increased in tumor tissues with lower ANO5 expression, while the expression of KI67 (a biomarker for proliferation) was decreased." (PMID 34238763, 2021). "Inhibition of ANO5 increased NELL1 and NELL2 expression in vivo and decreased tumor proliferation." (PMID 34238763, 2021).
cancer (5 papers, 2018 to 2024). A tumor composed of atypical neoplastic, often pleomorphic cells that invade other tissues. "The genes with the most significantly decreased expression in spleens from the Mg2800 diet group included Ano5 (anoctamin 5) and Gng4 (G protein subunit gamma 4), and both are associated with worse cancer outcomes and favor proliferation, migration, and invasion." (PMID 39683640, 2024). "Apart from ANO1, other members of the anoctamin family were also correlated with cell proliferation and cancer development, like ANO5 (TMEM16E), ANO7 (TMEM16G) and ANO9 (TMEM16J)." (PMID 30893776, 2019). "Previous studies on the role of ANO5 in cancer development have reported contradictory results." (PMID 34238763, 2021). "Additionally, ANO5 is known to participate in proliferation of myoblasts and some cancer cells." (PMID 36742392, 2023). "While ANO5, ANO7, and ANO9 may also be relevant for growth of cancers, evidence has been provided for a role of ANO6 (TMEM16F) in regulated cell death." (PMID 30893776, 2019).
bone disorder (4 papers, 2022). "Anoctaminopathy-5 refers to a group of clinically heterogeneous skeletal muscle or bone disorders due to mutations in ANO5." (PMID 36292621, 2022). "Anoctaminopathy-5 refers to a group of hereditary skeletal muscle or bone disorders due to mutations in the anoctamin 5 (ANO5)-encoding gene, ANO5." (PMID 36292621, 2022). "Dominant ANO5 mutations cause the bone disorder gnathodiaphyseal dysplasia 1 (GDD1)." (PMID 35563815, 2022). "Therefore, our research proposes ANO5 as a therapeutic target for counteracting the development of skeletal diseases related to GDD." (PMID 35982081, 2022).
genetic diseases (3 papers, 2015 to 2020). "Despite the clear links of ANO5 deficiency to these genetic diseases in patients, there is currently no animal model with ANO5 deficiency." (PMID 26693275, 2015).